MASP1 (MBL associated serine protease 1)
Diseases named in the same sentence as MASP1 in open-access papers (continued):
Sharing a sentence is not in itself a finding about the gene and the disease.
myocardial infarction (7 papers, 2017 to 2025). Gross necrosis of the myocardium, as a result of interruption of the blood supply to the area, as in coronary thrombosis. "In WB, we found MASP1, a gene associated with a decreased lectin pathway activity in acute myocardial infarction patients." (PMID 31688915, 2020). "In another study, a lower concentration of MASP-2 and a higher concentration of MASP-1 were observed in myocardial infarction patients compared to the ones in CAD patients." (PMID 38338844, 2024). "MASP1 concentration was increased in myocardial infarction, however, in IS was reported to be either increased or decreased, whereas in ICH and SAH, lower levels were found." (PMID 34975707, 2021). "A comparative study focused on levels of MBL and MASPs in patients with cardiovascular and cerebrovascular diseases observed that patients with a recent myocardial infarction had higher serum MASP-1 levels than healthy controls, coronary artery disease (CAD) patients, and stroke patients." (PMID 41155225, 2025). "In another study, lower MASP-2 and higher MASP-1 levels were observed in patients with myocardial infarction compared with patients with stable CAD and healthy controls (only MASP-1), whereas MAP-1 levels were similar in these groups." (PMID 29910807, 2018). "Interestingly, plasma MAp44 levels remain unaltered in patients with acute myocardial infarction, with elevated MASP-1 levels suggesting a poor protective response by MAp44." (PMID 41155225, 2025).
Arthritis (5 papers, 2014 to 2020). Inflammation of a joint. "Additional evidence for a role for MASP-1 in AP activation derived from studies in which the MASP-1/3–/– mice have been subjected to an AP-dependent model of arthritis." (PMID 24279761, 2014). "Accordingly, in an AP-dependent arthritis model, MASP-1/3–/– mice were protected from joint inflammation, and sera from these mice showed no activity in an AP-dependent assay in vitro." (PMID 24279761, 2014). "Mice lacking MASP-1/3 have no LP and have suboptimal AP activity and these mice are resistant to arthritis." (PMID 32153567, 2020). "Mice lacking C5 or treated with GalNAc-C5-siRNA or anti-C5 inhibitory antibody do not develop arthritis despite the presence of MASP-1 and MASP-2." (PMID 32153567, 2020). "Therefore, for this current study we used GalNAc-MASP-1-siRNA and GalNAc-MASP-2-siRNA duplexes targeting hepatocytes to examine their effect on arthritis." (PMID 32153567, 2020). "The role of MASP-1 and MASP-2 proteases in arthritis has been unknown." (PMID 32153567, 2020). "However, in there was a decrease (58%) in expression of MASP-3 in the liver from normal mice with arthritis treated with GalNAc-MASP-1-siRNA (data not shown) but not with GalNAc-MASP-2-siRNA (data not shown)." (PMID 32153567, 2020). "We evaluated the effects of N-acetylgalactosamine (GalNAc)-conjugated MASP-1 and MASP-2 duplexes in vitro and in mice with and without arthritis to examine whether knockdown of MASP-1 and MASP-2 expression affects the development of arthritis." (PMID 32153567, 2020).
leprosy (5 papers, 2013 to 2021). Leprosy is a chronic infectious disease affecting primarily the skin and peripheral nervous system. "Although the MASP1*AC_CTG presented a trend to a leprosy-restricted HBV association as well, this was not confirmed after correction for age and ethnic group distributions (OR = 0.14 [95%CI = 0.02–1.20], P = 0.074)." (PMID 33643280, 2020). "They further illustrate the complexity of the response mounted against the parasite, which places MASP1 products in the regulatory crossroad between the innate and adaptive arms of the immunological system, modulating leprosy susceptibility." (PMID 32240160, 2020). "We also confirmed the recently published association with leprosy disease and the MASP1*GC_CCG haplotype, obtained with the same group of patients (OR = 1.81 [95%CI = 1.25–2.64], P = 0.002)." (PMID 33643280, 2020). "Here, we add another pivotal piece in the leprosy parasite-host interaction puzzle: polymorphisms and serum levels of three different lectin pathway proteins, all encoded by the same gene, namely mannan-binding lectin-associated serine protease 1 (MASP1)." (PMID 32240160, 2020). "Furthermore, we identified an opposite association with the MASP1*GC_CCA haplotype, with leprosy resistance (OR = 0.50 [95%CI = 0.28–0.89], P = 0.019)." (PMID 33643280, 2020). "Given this context, we investigated whether MASP1 gene variants and products are associated with susceptibility to leprosy and to the different clinical forms of the disease." (PMID 32240160, 2020). "We also identified a genetic association between MASP-1 and MASP-3 serum levels and MASP1 polymorphisms within haplotypes associated with increased resistance and susceptibility to leprosy." (PMID 32240160, 2020). "The summed frequencies of MASP1*AC_CC haplotypes, diverging only at the most 3′ rs850314*G>A polymorphism, were higher among HBV+ leprosy patients compared to blood donors or HBV− leprosy patients." (PMID 33643280, 2020). "First, we assessed possible associations of MASP-1, MASP-3 and MAp44 levels with leprosy and the different clinical forms of the disease." (PMID 32240160, 2020). "On the other hand, MASP1 haplotypes associated with lower MASP-1 and higher MASP-3 levels at baseline were associated with leprosy resistance, probably by decreasing mycobacteria infection, which relies on successful complement-driven opsonization and phagocytosis." (PMID 33729332, 2021). "The CA, CG and TG haplotype combinations did not present any association with MASP-1 and MAp44 levels, although leprosy patients presented consistently lower MAp44 levels, regardless of the exon 12 genotype." (PMID 32240160, 2020).
prediabetes (5 papers, 2019 to 2025). "Bonferroni correction confirmed the positive association between MASP1, prediabetes, and fasting glucose levels." (PMID 40162315, 2025). "Mannan-binding lectin serine protease 1 (MASP1), which plays a role in the lectin pathway of the complement system, has been identified as a biomarker of prediabetes and is relevant to obesity, dyslipidemia and hypertension in cardio- and cerebrovascular patients." (PMID 32089734, 2020). "In prediabetes, type 1 and type 2 DM, plasma levels of MBL, MASP-1 and MASP-2 are elevated, and animal models have shown that MASP-1 levels rise just before the onset of DM symptoms." (PMID 33729332, 2021). "Nano-LC/MS in SRM mode (SRM-MS) identified positive correlations between MASP1, THBS1, GPLD1, and prediabetes, while ApoA-IV showed a negative association." (PMID 40162315, 2025).
Sepsis (5 papers, 2019 to 2025). Sepsis is defined as life-threatening organ dysfunction caused by a dysregulated host response to infection. "MASP-1 exhibits excellent diagnostic ability in multiple sepsis (AUC > 0.70) and trauma (AUC > 0.75) datasets." (PMID 38384415, 2024). "Increased MASP-1 activation and consumption are associated with severe coagulation disturbances in sepsis." (PMID 38384415, 2024). "We hypothesized that MASP-1 levels are associated with the initiation and severity of trauma and sepsis." (PMID 38384415, 2024). "MASP-1 exhibited excellent diagnostic values (AUC > 0.7) in multiple datasets and at multiple time points and could efficiently distinguish trauma/sepsis samples from the control samples." (PMID 38384415, 2024). "In this study, we found that MASP-1 showed superior diagnostic ability across multiple datasets and time points for trauma and sepsis and that it could effectively distinguish trauma/sepsis samples from control patient/healthy control samples." (PMID 38384415, 2024). "Furthermore, we collected clinical specimens to preliminarily validate the expression level and diagnostic efficacy of MASP-1 as well as the correlation of MASP-1 with clinical features of trauma and sepsis." (PMID 38384415, 2024). "Additionally, we investigated the association between MASP-1 expression and clinicopathological characteristics of trauma and sepsis." (PMID 38384415, 2024). "Moreover, MASP-1 exhibited excellent diagnostic ability (AUC > 0.7) in multiple datasets and time points and could effectively distinguish trauma/sepsis samples from the control samples." (PMID 38384415, 2024). "We obtained five sepsis, two trauma, and one sepsis and trauma RNA-sequencing dataset from the Gene Expression Omnibus (GEO) database and conducted a comprehensive evaluation of the expression pattern, biological functions, and diagnostic value of MASP-1 in trauma and sepsis." (PMID 38384415, 2024). "In addition, MASP-1 showed favorable diagnostic values for sepsis at multiple time points." (PMID 38384415, 2024). "Differential gene expression analysis of the multi-transcriptome data revealed that the mRNA levels of MASP-1 were significantly upregulated in trauma and sepsis samples compared to the control samples." (PMID 38384415, 2024). "The qRT-PCR analysis revealed that MASP-1 expression was significantly upregulated in the traumatic sepsis patients compared to the control patients (p = 0.02)." (PMID 38384415, 2024). "This is possibly due to the initial activation and subsequent depletion of MASP-1 in trauma-induced sepsis." (PMID 38384415, 2024). "An in-depth analysis of these transcriptome datasets revealed that MASP-1 was significantly upregulated in trauma/sepsis samples compared to the control samples." (PMID 38384415, 2024). "Functional enrichment analysis revealed that MASP-1 primarily promotes trauma and sepsis via the immune-related signaling pathway." (PMID 38384415, 2024). "The GO and KEGG enrichment analyses revealed that MASP-1 primarily mediated trauma/sepsis via the immune-related signaling pathway." (PMID 38384415, 2024). "The gene expression analysis of the trauma and sepsis cohorts from the GEO database revealed that the mRNA levels of MASP-1 were significantly (p < 0.05) upregulated in sepsis and trauma samples compared to the control samples." (PMID 38384415, 2024). "Further correlation analysis revealed that MASP-1 expression was significantly associated with B cells, CD8 T cells, neutrophils, and macrophages in trauma and sepsis." (PMID 38384415, 2024). "Further correlation analysis revealed a close association between MASP-1 expression, the proportion of CD8 T cells, and IL6/JAK/STAT3 signaling scores in trauma and sepsis." (PMID 38384415, 2024). "RT–qPCR and ELISA of clinical specimens further verified that MASP-1 expression was significantly higher in traumatic sepsis patients compared with the control patients." (PMID 38384415, 2024).
Sepsis (continued). "Our results indicate that MASP-1 is a potential immune-related biomarker for the diagnosis and disease severity of trauma and sepsis." (PMID 38384415, 2024). "To illustrate the potential mechanism of MASP-1 in the onset of trauma and sepsis, we performed Spearman’s correlation analysis between immune cells and common biological pathways." (PMID 38384415, 2024). "Our results suggest that MASP-1 can serve as an immune-related biomarker for the diagnosis and disease severity of trauma and sepsis." (PMID 38384415, 2024). "Altogether, these results indicate that several immune cells, especially CD8 T cells, neutrophils, and macrophages, are involved in MASP-1-mediated trauma and sepsis." (PMID 38384415, 2024). "To further verify the MASP-1 expression levels in trauma and sepsis, we performed qRT-PCR and ELISA of 63 clinical blood specimens." (PMID 38384415, 2024). "MASP-1 expression was significantly upregulated in the trauma/sepsis samples compared to the control samples in the GEO datasets." (PMID 38384415, 2024). "Altogether, our results indicate that MASP-1 can serve as a robust biomarker for early diagnosis of traumatic sepsis." (PMID 38384415, 2024). "In the present study, we comprehensively analyzed the role of MASP-1 in trauma and sepsis using five sepsis (GSE54514, GSE57065, GSE95233, GSE131761, and GSE154918), two trauma (GSE11375 and GSE64711), and one sepsis and trauma (GSE69063) GEO datasets." (PMID 38384415, 2024). "Therefore, we propose that MASP-1 triggers traumatic sepsis by activating the IL6/JAK/STAT3 signaling pathways and promoting CD8 T-cell depletion after traumatic injury." (PMID 38384415, 2024). "Additionally, MASP-1 expression was significantly positively correlated with the severity of trauma and sepsis (APACHE-II and neutrophil proportion)." (PMID 38384415, 2024). "Additionally, Pearson’s correlation analysis identified 123 and 393 MASP-1-related DEGs in sepsis and trauma samples, respectively, among which 98 were shared between the two." (PMID 38384415, 2024). "Similarly, ELISA showed that MASP-1 was significantly higher in the traumatic sepsis patients compared with the control patients (p = 0.026)." (PMID 38384415, 2024). "We speculated that MASP-1 can identify early stages of post-traumatic sepsis and reflect the natural history of the traumatic sepsis condition." (PMID 38384415, 2024). "Additionally, MASP-1 expression was significantly higher in sepsis and head trauma samples compared with the healthy controls in the GSE69063 cohort." (PMID 38384415, 2024). "Therefore, determining the role of MASP-1 in the development of trauma and sepsis is of particular clinical relevance as it can facilitate their early detection and treatment." (PMID 38384415, 2024). "Moreover, qRT-PCR and ELISA results further confirmed that MASP-1 expression was significantly upregulated in traumatic sepsis patients than in control patients and that it exhibited superior diagnostic accuracy than general clinical biomarkers, such as CRP and PCT." (PMID 38384415, 2024). "First, our validation cohort was a single-center cohort with a limited sample size, which may not be generalizable; therefore, further validation using multicenter prospective cohorts with large sample sizes is necessary for the clinical application of MASP-1 in traumatic sepsis." (PMID 38384415, 2024). "Further correlation analysis revealed that MASP-1 expression was significantly positively associated with IL6/JAK/STAT3 signaling and significantly negatively correlated with checkpoint, ferroptosis, HLA, T-cell co-inhibition, T-cell co-stimulation, and necrosis in trauma and sepsis." (PMID 38384415, 2024). "Further correlation analysis revealed that MASP-1 expression was significantly negatively associated with B cells, CD8 T cells, ILs, T helper (Th) cells, and Th1 cells and significantly positively correlated with macrophages, neutrophils, and Tregs in trauma and sepsis." (PMID 38384415, 2024).
Sepsis (continued). "Interestingly, PCA revealed that MASP-1 expression could completely distinguish trauma/sepsis samples from the control patient/healthy samples." (PMID 38384415, 2024). "However, the role of MASP-1 in trauma and post-traumatic sepsis remains largely elusive." (PMID 38384415, 2024). "Thereafter, we systematically analyzed the association between MASP-1, immune cell infiltration (ICI), and immune-related molecular pathways, and based on these results, we proposed an underlying mechanism of the regulatory role of MASP-1 in the occurrence of trauma and sepsis." (PMID 38384415, 2024). "Furthermore, we observed a minor decrease in AUC values over time in various time point datasets, suggesting that MASP-1 may be suitable for the early identification of trauma and sepsis." (PMID 38384415, 2024). "However, the effects of MASP-1 on post-traumatic sepsis remain unclear." (PMID 38384415, 2024). "If MASP-1 proves to be an indeed important player in HAE, sepsis, and ischemia/reperfusion, it can be a promising target for drug development." (PMID 31130964, 2019). "Finally, further in vitro and in vivo experiments should be conducted in future studies to elucidate the regulatory mechanisms and functional roles of MASP-1, CD8 T cells, and IL6/JAK/STAT3 signaling pathways in trauma and sepsis." (PMID 38384415, 2024). "Furthermore, Spearman’s correlation analysis revealed that MASP-1 expression was significantly negatively correlated with naive B cells, naive CD4 T cells, and CD8 T cells and significantly positively correlated with M0 macrophages, monocytes, and neutrophils in trauma and sepsis." (PMID 38384415, 2024). "However, the potential effects of MASP-1 in trauma and sepsis have not yet been explored." (PMID 38384415, 2024).
cervical cancer (4 papers, 2018 to 2023). A primary or metastatic malignant neoplasm involving the cervix. "In conclusion, our study shows that high MASP-2, MASP-1, and MAp-19 serum levels are associated with cervical cancer progression and worse disease prognosis." (PMID 30532757, 2018). "A previous study has reported that the expression of MASP-1 is significantly increased in cervical cancer patients, HPV-positive patients and cervical secretory tissues with late FIGO stage (stage III - IV)." (PMID 37519786, 2023). "In this investigation, we determined the serum levels of MASP-1, MASP-2, MASP-3, MAp-44, and MAp-19 in patients with cervical cancer and cervical intraepithelial neoplasia (CIN)." (PMID 30532757, 2018). "Similarly, the expression of MASP-1 in invasive cervical cancer is significantly higher than that in precancerous lesions, and higher serum levels of MASP-1 are associated with poor prognosis in cervical cancer." (PMID 37519786, 2023). "MASP1 is related to immune cell infiltration in head and neck cancer and could be a candidate target gene in lung cancer and cervical cancer." (PMID 37106442, 2023). "The role of MASP-1 in cervical cancer progression has been established." (PMID 35846149, 2022). "Our study demonstrates that MASP-2, MASP-1, and MAp-19 could have a role in the progression of cervical cancer." (PMID 30532757, 2018). "The present study revealed that the N-glycopeptide of MASP1, LUM, ATRN, CO8A, CO8B and CO6 may be potential biomarkers for predicting the efficacy of chemotherapy for cervical cancer." (PMID 37519786, 2023).
diabetes (4 papers, 2015 to 2023). "In this way MASP-1 could contribute to thrombotic complications which are frequent in diabetes and other inflammatory diseases." (PMID 26645987, 2015).
Stroke (4 papers, 2015 to 2024). Sudden impairment of blood flow to a part of the brain due to occlusion or rupture of an artery to the brain. "This study provides a comparative analysis of the phenotypes of mouse lines with targeted deficiencies of the LP-specific serine proteases MASP-1, MASP-2, and MASP-3 in a mouse model of stroke." (PMID 27577570, 2016). "This work defines the contributions of each of the three LP-associated enzymes—mannan-binding lectin-associated serine protease (MASP)-1, MASP-2, and MASP-3—to ischemic brain injury in experimental mouse models of stroke." (PMID 27577570, 2016). "Based on our data, we suggest that CPN2, FXII, PLG, MASP1, APCS, PON1, and CA1 for IS and FBLN1 and GRN for ICH should be further scientifically pursued as potential stroke blood biomarkers." (PMID 34975707, 2021). "In summary, hypoxia potentiates the effect of MASP-1 on ECs, at least partially by increasing PAR expression, resulting in interaction at several levels, which may altogether exacerbate stroke and AMI progression." (PMID 38937560, 2024).
Cognitive impairment (3 papers, 2013 to 2024). Abnormal cognition is characterized by deficits in thinking, reasoning, or remembering. "In aggregate, the study demonstrated that inhibition of MASP-2, but not of MASP-1, improved the cognitive deficits in the TBI mice with a modest protection of the sensorimotor functions." (PMID 38807149, 2024).
congenital heart disease (3 papers, 2019 to 2022). A heart disease that is present at birth. "Here we report an investigation of pre-operative serum MASP-1, MASP-2, MASP-3, MAp44, MAp19 and ficolin-3, concentrations and their possible influence on the incidence of post-operative complications in infants and children operated on because of congenital heart disease." (PMID 30814659, 2019).